ENSG00000261732 (novel protein)
Gene: Protein-coding gene on chromosome 16 (1,632,259 to 1,686,715, forward strand). Ensembl gene ENSG00000261732.
Genetic constraint (gnomAD): Missense variants: 47 observed, 55.93 expected, observed/expected ratio (o/e) 0.84, 90% interval 0.66 to 1.07. Synonymous variants: 23 observed, 19.02 expected, observed/expected ratio (o/e) 1.21, 90% interval 0.87 to 1.7.